AQP4 (aquaporin 4)
Diseases named in the same sentence as AQP4 in open-access papers (continued):
Sharing a sentence is not in itself a finding about the gene and the disease.
myelitis (continued). "Approximately half of our rheumatologic disease cohort with myelitis unrelated to MS had AQP4-IgG seropositive NMOSD while MOGAD accounted for a small but clinically relevant proportion of patients." (PMID 39442039, 2025). "Episodes of ON (unilateral or bilateral) all preceded initial myelitis presentations, with ON in 9 (45%) of 20 patients with AQP4-IgG seropositive NMOSD vs 1 (6%) of 17 “double-seronegative” patients (p = 0.011) and 1 (33%) of 3 patients with MOGAD." (PMID 39442039, 2025). "In contrast to brain lesions, inflammatory spinal cord lesions in the context of myelitis attacks occur in a large majority of patients with AQP4-IgG+ NMOSD." (PMID 41362332, 2025). "We clinicoradiologically and serologically characterized patients with myelitis associated with rheumatologic disease evaluated in the era of availability of MOG-IgG and more sensitive AQP4-IgG cell-based assays." (PMID 39442039, 2025). "Our patient, a 49-year-old woman, displayed MRI findings of continuous central spinal cord hyperintensities and clinical symptoms of ON and myelitis, along with positive AQP4-IgG in serum and CSF." (PMID 38899058, 2024). "MOGAD myelitis can be very severe at nadir, similarly to AQP4 + NMOSD myelitis (Expanded Disability Status Scale (EDSS) ≥ 7 in over 30%)." (PMID 38804311, 2024). "Our case series including two AQP4-IgG + NMOSD patients revealed SC GM% increased by roughly 2% with either a myelitis or optic neuritis attack between visits." (PMID 38343712, 2024). "Differential diagnosis: Some SLE patients with myelitis test positive for anti-aquaporin-4 antibodies, indicating the presence of comorbid NMOSD." (PMID 39355071, 2024). "Our findings are consistent with the literature showing that MOGAD has a lower clinical myelitis incidence with a smaller chronic lesion burden and a lower impact of chronic pain syndromes than AQP4-IgG + NMOSD." (PMID 38343712, 2024). "The clinical features of GFAP/AQP4-IgG double-positive myelitis include urinary retention and sensory disturbances." (PMID 39975853, 2024). "Recently, so-called BSL, defined as hyperintense lesions on axial T2-weighted images and sometimes associated with T1 low signal, have been reported to strongly favor a diagnosis of (especially AQP4-IgG-positive) NMOSD in patients presenting with myelitis." (PMID 37022481, 2023). "Subjects with AQP4+NMOSD are overall more likely to experience partial, often poor recovery from each myelitis attack, and a myelitis presentation is associated with greater likelihood of reaching severe motor disability compared to isolated ON." (PMID 36419536, 2022). "ON was the most represented first clinical event in our entire cohort (more often bilateral in anti-MOG than anti-AQP4 in larger cohorts than ours), followed by myelitis and the simultaneous attack of both regions." (PMID 34097296, 2022). "Seven patients (7/28, 25.0%) in the AQP4-ON group had a clinical history of myelitis, with myelitis occurring less frequently in the MOG-ON (1/26, 3.8%) and IDON (0/29, 0.0%) patients (P = 0.002)." (PMID 35615385, 2022). "In the same study, a slightly higher frequency of asymptomatic spinal cord lesions were observed on MRI scans acquired in concomitance with non-myelitis attacks (3/331, 0.9% in AQP4+NMOSD and 11/151, 7.3% in MOGAD)." (PMID 36419536, 2022). "Two AQP4-NMOSD patients relapsed with isolated myelitis and one relapsed with simultaneous unilateral ON and myelitis." (PMID 34097296, 2022). "After the acute phase of the myelitis, both clinical and MRI evolution vary substantially between AQP4+NMOSD, MOGAD and MS." (PMID 36419536, 2022). "Characteristic of MOGAD myelitis compared to AQP4+NMOSD is a greater frequency of sphincter dysfunction likely due to a more frequent involvement of the lower portions of the spinal cord." (PMID 36419536, 2022).
myelitis (continued). "In our study, symptoms of myelitis were more predominant in patients with AQP4-abs than in those with MOG-abs either at onset or relapse, but LETM did not help distinguish between the two groups, similar to other reports." (PMID 33841310, 2021). "We identified 2 case reports and 1/10 patients in a case series with MOG antibody-associated myelitis in association with a VZV infection; in addition, there are 9 reports of AQP4 antibody-associated CNS disorders in patients with VZV infections." (PMID 34737756, 2021). "AQP4-ab-positive patients were more likely to present with myelitis (p = 0.001), bladder or bowel dysfunction (p = 0.018), dyskinesias (p = 0.018), and paresthesia (p = 0.001) at onset." (PMID 33841310, 2021). "Covariates including age, AQP-4 status, history, annualized relapse rate, the length of myelitis, periventricular lesion, and brain lesion volume all entered the linear regression model." (PMID 32973658, 2020). "A higher prevalence of myelitis with clinical attacks and chronic spinal cord lesions was detected for AQP4-IgG-seropositive NMOSD patients in comparison to MOG-IgG-associated diseases." (PMID 31345223, 2019). "Similar to AQP4-IgG-positive myelitis, more than one lesion in the same MRI and swelling of the spinal cord were detected in many patients at least once." (PMID 27793206, 2016). "Five anti-AQP4 (+) patients (35.71 %) experienced recurrent brainstem symptoms before the attacks of ON or myelitis, while only one anti-AQP4 (-) patients (5.88 %, p = 0.05) had more than one brainstem attacks." (PMID 27769253, 2016). "MOG-IgG-positive ON and myelitis are increasingly recognized as important differential diagnoses of AQP4-IgG-positive NMOSD." (PMID 27793206, 2016). "In the present study, we aimed to assess the frequency of asymptomatic acute brain MRI abnormalities accompanying ON or myelitis in NMOSD patients with antibodies to aquaporin-4 (termed AQP4-Ab)." (PMID 27936193, 2016). "Among the 37 NMO-ON patients, 5 had previous myelitis and all patients showed a seropositive for AQP4-Ab." (PMID 26649191, 2015). "In all anti-AQP4-positive patients, the nature of relapses developed after commencing fingolimod appeared to be similar to previous relapses (myelitis in patients 1, 2 and 3, and multifocal cerebral and cerebellar white matter lesions in patient 4)." (PMID 24475777, 2014). "Serum anti-AQP4 M-23 IgG Abs were specifically detected in 29 NMO patients, 17 patients with high risk NMO and two patients with myelitis due to demyelination (CIS) and SLE." (PMID 20463974, 2010). "We hypothesized that more sensitive AQP4-IgG assays and availability of MOG-IgG testing would identify AQP4-IgG seropositive NMOSD and MOGAD as prevalent causes of myelitis (particularly LEM) in patients with rheumatologic diseases." (PMID 39442039, 2025). "AQP4-IgG+ clinical attacks with BS had lower attack titres compared to myelitis (P = 0.002)." (PMID 40933287, 2025). "Five cases (2 men and 3 women) were complicated by myelitis, of which 3 were AQP4-Ab positive." (PMID 40377800, 2025). "The presence of AQP4-IgG seropositivity and LETM may help differentiate NMOSD from SLE-associated myelitis." (PMID 40491913, 2025). "This could explain why central neuropathic pain is more severe in AQP4-positive myelitis patients and why neuropathic pain is more common in NMOSD compared to other CNS demyelinating diseases." (PMID 39768745, 2024). "Additionally, GFAP-IgG myelitis exhibits distinct spinal cord lesions, often longitudinally extensive, centrally located, and showing subtle imaging features compared to AQP4-IgG lesions." (PMID 39328614, 2024). "An additional diagnostic clue could be the identification of antibodies associated with myelitis, such as MOG‐IgG and AQP4–IgG." (PMID 39222058, 2024).
myelitis (continued). "While myelitis is typically longitudinally extensive—extending over three or more complete vertebral segments—in both AQP4-IgG-positive and AQP4-IgG-negative NMOSD (and MOG-EM/MOGAD) long lesions are extremely rare in MS and, if present, usually result from the coalescence of adjacent lesions." (PMID 37022481, 2023). "Interestingly, while most patients had MS or CIS, there were also 3 patients with aquaporin-4-IgG (AQP4) positive NMOSD, and one patient with MOG-IgG associated myelitis." (PMID 36247761, 2022). "MBP was found to be higher in both MOGAD and AQP4-IgG NMOSD patients when compared to MS, although this association was not consistent with a previous study showing MBP correlation with EDSS and length of myelitis." (PMID 35401423, 2022). "MRI showed myelitis of more than three spinal segments, and serum AQP4 was positive." (PMID 34520629, 2021). "Bright spotty lesions, which have been reported in 27% to 54% of patients with AQP4 antibodies–associated myelitis, were absent in all children with MS and MOGAD in our cohort, underscoring their utility as a distinguishing feature between these diseases." (PMID 34643718, 2021). "In 2004, a groundbreaking discovery came from a research group of Mayo Clinic that showed the presence of AQP4-IgG in the serum of patients who previously had “atypical” MS that exclusively presented recurrent ON and/or myelitis." (PMID 33013632, 2020). "Lupus Myelitis may be difficult to differentiate from SLE with NMOSD myelitis, thus evaluation of serum AQP4-IgG is essential in patients with lupus related myelitis." (PMID 32671002, 2020). "Although the effectiveness of these monoclonal antibodies in NMOSD mainly target myelitis, they may be also promising to retard ON relapses in patients with the AQP4 antibody." (PMID 33628473, 2020). "Longitudinally extensive myelitis affecting more than three vertebral segments on cervical MRI and positive serum AQP4‐IgG may be indicative of NMO." (PMID 32755074, 2020). "Radiological evolution of myelitis (from short myelitis to LETM) over the first 12 days from presentation in a patient with AQP4-Ab NMOSD highlights that consideration of the timing of imaging is key and the time point to radiological nadir may be variable." (PMID 30671648, 2019). "In addition, anti-AQP4 (+) ABS patients are prone to have recurrent brainstem symptoms before attacks of ON or myelitis." (PMID 27769253, 2016). "Myelitis, comparison of clinical features according to the patients' AQP4-Ab serostatus." (PMID 22260418, 2012). "Myelitis, comparison of spinal cord MRI features according to the patients' AQP4-Ab serostatus." (PMID 22260418, 2012). "In addition, AQP4-IgG (titer 1:640) was detected in one patient with clinically isolated syndrome (CIS) presenting with myelitis." (PMID 22204662, 2011). "Additionally, M-23 AQP4-IgG was detected in two patients with myelitis due to demyelination (CIS) and SLE, respectively." (PMID 20463974, 2010). "Supporting the view that interpretation of imaging is a particularly challenging aspect of diagnosis, many of the study neurologists did not accurately identify some typical/suggestive NMOSD MRI lesions in AQP4-IgG-seronegative and unknown status, except for ON, myelitis, or APS lesions." (PMID 39735550, 2024). "In addition, ICI-triggered AQP4+ myelitis might have worse prognosis than those cases that resemble MS lesions (short segment myelitis), although this requires further research." (PMID 36247761, 2022). "In 5 out of 14 patients (36 %) with a history of simultaneous brainstem encephalitis and myelitis and available MRI data, lesions contiguously stretched from the medulla oblongata into the cervical cord at least once, similar to what can be seen in AQP4-IgG-positive patients." (PMID 27802825, 2016).
myelitis (continued). "Our study confirms weaker binding of NMO-IgG to full length AQP4, resulting in a lower sensitivity for clinically definite NMO (70%) and high risk NMO (39%) patients, besides also the M-23 IgG seropositive patient with SLE associated myelitis was negative for full length AQP4-IgG." (PMID 20463974, 2010). "Of these 18, 3 were diagnosed with AQP4-IgG seronegative NMOSD, 1 neuro-Behçet disease, and 14 other (unclassifiable) myelitis." (PMID 39442039, 2025). "Although A-GFAP-A can lead to longitudinal extensive myelitis, there were few reports of permanent paraplegia or quadriplegia in A-GFAP-A, while AQP4 positive neuromyelitis spectrum disease (NMOSD) can result in permanent paralysis." (PMID 39911384, 2025). "In a study comparing outcomes of myelitis attacks between AQP4 + NMOSD and MOGAD, the median EDSS at myelitis recovery was 3.0 (range 1.0–8.0) for AQP4 + NMOSD and 1.8 (range 1–8.0) for MOGAD." (PMID 38804311, 2024). "Meanwhile, 47% (8 of 17) of AQP4-IgG + NMOSD and only 13% (1 of 8) of MOGAD patients with previous myelitis reported neuropathic pain." (PMID 38343712, 2024). "Myelitis attacks in MOGAD are also frequently severe at nadir, approaching the disability observed in AQP4+NMOSD attacks (EDSS ≥ 7 in over 30%)." (PMID 36419536, 2022). "Complete resolution of T2 hyperintense spinal cord lesions is uncommon in both MS and AQP4+NMOSD, while it is observed in 62–79% of MOGAD myelitis lesions." (PMID 36419536, 2022). "The initial clinical event in AQP4-NMOSD was unilateral ON (N = 4), myelitis (N = 3), bilateral ON (N = 2), or simultaneous myelitis and ON (N = 1)." (PMID 34097296, 2022). "The initial clinical event in AQP4-NMOSD is, by decreasing frequency, unilateral ON, myelitis, bilateral ON, myelitis plus ON, brainstem (mainly an area postrema syndrome) and supra-tentorial lesions." (PMID 34097296, 2022). "The H-sign has been reported in 30–60% of MOGAD myelitis, and helps in distinguishing MOGAD from AQP4+NMOSD, where it is observed in 33% of cases, and particularly MS, where its occurrence is exceptionally rare." (PMID 36419536, 2022). "The MOG-IgG- group had a clinical diagnosis as follows: 25.9% had ON, 27.6% had myelitis, 3.5% were clinically diagnosed with seronegative NMOSD, 5.2% were diagnosed with AQP4-NMOSD." (PMID 34025652, 2021). "A patient with extensive myelitis is more likely to be tested for AQP4 serostatus and correctly identified as NMOSD than an individual with shorter myelitis or an isolated ON." (PMID 31171648, 2019). "The recent discovery of AQP4-IgG in patients with NMO has revived interest in the co-occurrence of eye disorders and myelitis." (PMID 31883522, 2019). "Serum laboratory testing for anti-AQP4 and MOG antibodies through cell-based assays should be considered in any child with myelitis, as a positive result would be clinically significant in relation to ongoing surveillance and management." (PMID 31109018, 2019). "Eight MOG-IgG-positive patients had a previous diagnosis of AQP4-IgG-negative NMOSD with ON and myelitis, and eight of (mainly recurrent) ON." (PMID 27802824, 2016). "We reviewed 324 brain MRI scans that were obtained during acute attacks of ON or myelitis, in 165 NMOSD patients with AQP4-Ab." (PMID 27936193, 2016). "Two patients with myelitis (2/4, 50%) were NMO-IgG/anti-AQP4 positive; the first had Neuromyelitis Optica (NMO), while the other had Longitudinal Extensive Transverse Myelitis (LETM), which belongs to the NMO spectrum of disorders." (PMID 23424638, 2013). "Although ON and myelitis attacks tend to be less severe in MS than in NMOSD on average (at least in AQP4-IgG-positive cases), mild attack-related symptoms should not per se be (mis)taken as evidence against a diagnosis of NMOSD." (PMID 37022481, 2023). "Less commonly, NMOSD with AQP4‐IgG can present with APS and progressive to myelitis." (PMID 37415585, 2023).
myelitis (continued). "Spinal cord areas not previously affected by lesions and AQP4+NMOSD patients without history of myelitis showed comparable metrics to healthy controls." (PMID 36419536, 2022). "Variable degree of spinal cord atrophy can be detected on clinical images in subjects with MS, but spinal atrophy is often a prominent feature on spine MRI exams acquired during remission in subjects with AQP4+NMOSD and history of myelitis, particularly at the level of spinal cord lesions." (PMID 36419536, 2022). "Participants with poor-quality images and final diagnoses of nondemyelinating disease, anti–aquaporin 4 antibody positivity, and relapsing seronegative myelitis were excluded." (PMID 34643718, 2021). "Spinal MRI revealed myelitis at Th7–10, while aquaporin-4 (AQP4) was negative in serum and cerebrospinal fluid." (PMID 34960150, 2021). "Spinal cord atrophy and reductions of MUCCA are a consistent feature of AQP4 ab–positive NMOSD even in the absence of myelitis attacks/spinal cord lesions." (PMID 32625158, 2020). "The presence or absence of ‘short’ lesions in patients with AQP4-IgG- or MOG-IgG-positive myelitis is thought to depend, among other factors, on timing issues." (PMID 27793206, 2016). "By contrast, necrotic lesions leading to spinal cord cavitation, as sometimes noted in AQP4-IgG-positive myelitis, were not reported in any of our MOG-IgG-positive patients." (PMID 27793206, 2016). "ON was the first symptom in all children and no prior myelitis attacked in children with seropositive AQP-4 antibody." (PMID 27725883, 2016). "An AQP4 antibody negative female patient had very high titers of TG-Ab and TPO-Ab, and these fluctuating levels were associated with myelitis relapse." (PMID 25093326, 2014). "Recent studies have shown that brainstem involvement is quite common in patients with AQP4 autoimmunity, and cases of AQP4 antibody-positive ‘neuroencephalitis optica’ without concomitant myelitis indeed occur." (PMID 23320783, 2013). "However, no statistical significance was detected in the seropositivity to AQP4-ab, age of onset age, duration of disease, ARR, the first year of ARR (ARR1), the number of total attacks, and the attacks of ON, myelitis, and other lesions, as well as the type of first attack." (PMID 38994358, 2024). "In addition, lesions in MOGAD myelitis are frequently confined to the grey matter, resulting in the characteristic H-shape, as opposed to AQP4 + NMOSD, where lesions are centrally located, but involve both the grey and the white matter." (PMID 38804311, 2024). "Many participants missed typical/suggestive NMOSD MRI lesions, which are also additional MRI requirements for NMOSD with negative AQP4-IgG and NMOSD with unknown AQP4-IgG status, except for ON, myelitis, and APS lesions." (PMID 39735550, 2024). "Myelitis in NMOSD may also mimic spinal cancer or lymphoma and vice versa; whenever possible, AQP4-IgG (and MOG-IgG) should be tested and NMOSD excluded before a decision is made to perform spinal cord biopsy—a procedure that can leave patients severely disabled—for suspected spinal neoplasia." (PMID 37022481, 2023). "In a study comparing outcomes of myelitis attacks in AQP4+NMOSD and MOGAD, the median EDSS at myelitis recovery was 3.0 (range 1.0–8.0) for AQP4+NMOSD and 1.8 (range 1–8.0) for MOGAD, with only 7% of patients having an EDSS ≥ 6 at recovery in the MOGAD group vs. 44% of the AQP4+NMOSD." (PMID 36419536, 2022). "Similar to brain lesions, acute gadolinium enhancement is often nonspecific, differing from other myelitis for which characteristic enhancement patterns have been described (e.g., “elongated ring” in AQP4-IgG+NMOSD, dorsal subpial enhancement and “trident sign” in spinal cord sarcoidosis)." (PMID 35785363, 2022).